ARF1 (ARF GTPase 1)
Diseases named in the same sentence as ARF1 in open-access papers (continued):
Sharing a sentence is not in itself a finding about the gene and the disease.
tumor (40 papers, 2008 to 2025). "Through single‐cell sequencing, the remodeling of the tumor immune microenvironment induced by these new Arf1 inhibitors is analyzed and an increase in tumor‐associated CD8+ CD4+ double‐positive T (DPT) cells is identified." (PMID 39225354, 2024). "We then studied the relationship between the activated PPARγ pathway and NF-κB pathway in Arf1-deficient tumor cells." (PMID 39872623, 2023). "Curiously, LM11 seems to be ineffective when tumor cells carry a K38A substitution in Arf1, thus it is essential that Arf1 overexpressing tumors be tested for variants before the use of this inhibitor." (PMID 30884855, 2019). "Studies have shown that the mTOR pathway promotes tumor proliferation and metabolism, and that asparagine can activate mTORC1 through Arf1." (PMID 40781327, 2025). "The same group performed in vivo studies and showed that ARF1 promotes primary tumor growth and the formation of metastases." (PMID 38533085, 2024). "Demonstrations indicated that these newly designed Arf1 inhibitors exhibit low toxicity and robust anti‐tumor activities in various mouse tumor models, including liver, colon, breast, and melanoma, as well as PDX tumor models." (PMID 39225354, 2024). "We found that the released ATP level was also significantly increased in tumor cells with DU101 or DU102 treatment or Arf1 knockdown, which further stimulated T cell activation through P2RX7." (PMID 39225354, 2024). "We also reported that Arf1 knockdown in tumor cells resulted in the release of DAMPs, including ATP2." (PMID 39225354, 2024). "By detecting the phosphorylation level of well‐established TCR downstream kinases including ZAP70, LAT, and ERK, we found that T cells were activated after culturing with medium from tumor cells treated with either DU101 or DU102 or with Arf1 knockdown." (PMID 39225354, 2024). "DU101 or DU102 treatment did not further affect tumor and body weights in the Arf1‐deficient CT26 cell tumor‐bearing mice, indicating that DU101 and DU102 were specific Arf1 inhibitors." (PMID 39225354, 2024). "In the isotype treatment groups, a remarkable reduction in tumor size and a significant decrease in tumor weight were observed in mice that received the Arf1‐ablated tumor cells in comparison with mice that received the control tumor cells." (PMID 37786300, 2023). "For doing this, the DC2.4 cells were first pre‐cocultured with either the control or Arf1‐ablated tumor cells in the presence of ovalbumin (OVA) and then re‐cocultured with naïve CD8+ T cells isolated from the spleens of OT1 mice." (PMID 37786300, 2023). "First, we co‐cultured these gene‐knockout dendritic cells with either the Arf1‐ablated tumor cells or scrambled control tumor cells for 24 h to induce dendritic cell activation." (PMID 37786300, 2023). "We recently found that ablation of the Arf1-mediated lipid metabolism not only kills CSCs but also elicits an anti-tumor immune response." (PMID 39872623, 2023). "Our above data demonstrated that the Arf1‐ablated tumor cells induced activation of the NF‐κB, NLRP3 inflammasome, and cGAS‐STING triple pathways in DCs." (PMID 37786300, 2023). "Meanwhile, the amount of HMGB1 in the culture medium of the Arf1‐ablated tumor cells was significantly increased." (PMID 37786300, 2023). "In our study, we found that inhibition of Arf1 in tumor cells significantly upregulated the unsaturated fatty acids (LPE)." (PMID 39872623, 2023). "We observed a significant increase in the frequency of PD1+CD8+ T cells in tumors of mice bearing the Arf1‐ablated tumor cells, whereas the increase was completely abolished after treatment with both anti‐IFNAR1 and anti‐IL‐1β antibodies." (PMID 37786300, 2023). "Here, the authors identify a super signaling complex in DCs that mediates the Arf1‐ablation‐induced anti‐tumor immunity." (PMID 37786300, 2023). "Increased MIF, CNN2, and ARF1 are enriched in IL-12-related pathways, which promote tumor development." (PMID 38072118, 2023).
tumor (continued). "They find that the Arf1‐ablated tumor cells release OxLDL, HMGB1, and genomic DNA, which together bound to a coreceptor complex of CD36/TLR2/TLR6 on DC surface." (PMID 37786300, 2023). "In line with this, the concentration of oxidized low‐density lipoprotein (oxLDL), which contains oxidized lipids, was markedly increased in the supernatants of the Arf1‐ablated tumor cells in comparison with that in the control cells." (PMID 37786300, 2023). "Further, we demonstrated that the Arf1 inhibitors and programmed cell death protein 1 (PD-1) blockade reduce tumor growth synergistically." (PMID 39872623, 2023). "We found that the Arf1‐ablated tumor cells release oxLDL, HMGB1‐gDNA complex, and also induce expression of CD36, TLR2, and TLR6 in DCs." (PMID 37786300, 2023). "Together, these results demonstrated that the Arf1‐ablated tumor cells induced the activation of the cGAS‐STING signaling pathway in DCs both in vitro and in vivo." (PMID 37786300, 2023). "The increased level of LPE in the Arf1-deficient tumor cells sequestrated PPARγ from the PPARγ-NF-κB complex, which freed NF-κB for regulating CCL5 and T-cell tumor infiltration." (PMID 39872623, 2023). "Next, we sought to identify factors released from the Arf1‐ablated tumor cells that activated the triple pathways in DCs." (PMID 37786300, 2023). "Collectively, these data together demonstrated that Arf1 ablation in tumor cells promotes migration of the CD3+ T cells through the NF-κB-CCL5-CCR5 pathway." (PMID 39872623, 2023). "We also observed that the depletion of IL‐1β cytokine and type I IFNs abrogated tumor regression induced by the Arf1‐ablated tumor cells in mice." (PMID 37786300, 2023). "Knockdown of Il1b or Ifna/b in dendritic cells significantly blocked the induction of T cell stemness marker TCF1 by the Arf1‐ablated tumor cell‐challenged dendritic cells." (PMID 37786300, 2023). "Taken together, these data clearly demonstrated that the Arf1‐ablated tumor cells induced NLRP3 inflammasome activation in the co‐cultured DCs." (PMID 37786300, 2023). "Mechanically, Arf1 ablation in tumor stem cells induces mitochondrial disorder and the release of DAMPs, which recruit and activate DCs at tumor sites." (PMID 36172157, 2022). "The removal of Arf1 (a mediator of lipid metabolism to maintain the abundance of tumor stem cells) induces DC cell activation and activated DC cells increase CD8+ T cells’ infiltration to kill tumor cells." (PMID 36172157, 2022). "A microarray containing 202 cases of CRC tumor tissues and 158 cases of adjacent normal tissues was used to analyze ARF1 expression by immunohistochemistry and determine its correlation with patients' clinicopathological parameters." (PMID 33408784, 2021). "Immunohistochemistry, gain- and loss-of-function experiments, WST-1, colony-formation, immunoprecipitation, and tumor xenograft assays were used to examine the functional and clinical significance of ARF1 in colon tumorigenesis." (PMID 33408784, 2021). "Consistent with the in vitro data, Western blotting analysis of tumor xenografts showed ARF1 knockdown inactivated ERK signaling and decreased p-Drp1 expression." (PMID 33408784, 2021). "The ARF1 activation assay showed a significantly lower expression of ARF1-GTP, the active form of ARF1, not only in cells, but also in the tumor xenografts treated with azelastine, indicating that azelastine inhibited the activity of ARF1." (PMID 33408784, 2021). "The top genes in cold tumor are ARF1, PDIA3, ALDOA, FKBP2, NDUFS5, NDUFC1, COX7A2, C14orf2, LNX1, and BTBD6." (PMID 33816503, 2021). "Our results reveal that Arf1-pathway knockdown not only kills CSCs but also elicits a tumor-specific immune response that converts dying CSCs into a therapeutic vaccine, leading to durable benefits." (PMID 31924786, 2020). "We also found that the anti-tumor effect of Arf1 knockdown in wild-type mice was lost in both the DCs-KO and P2RX7-KO mice." (PMID 31924786, 2020).
tumor (continued). "The Golgi apparatus has been recognised for its central role in tumour cell survival, which is regulated by ARF1 activated by ARF guanine nucleotide exchange factors." (PMID 32616892, 2020). "We found that the anti-tumor effect of Arf1 knockdown in wild-type mice was lost in both the Rag1-KO and INFγ-KO mice." (PMID 31924786, 2020). "Collectively, these data suggest that Arf1 ablation induces its anti-tumor effect through ATP and HMGB1." (PMID 31924786, 2020). "Here we demonstrate that the Arf1-mediated lipid metabolism sustains cells enriched with CSCs and its ablation induces anti-tumor immune responses in mice." (PMID 31924786, 2020). "Collectively, these data suggest that the Arf1 ablation-induced anti-tumor immune responses occur through ER stress and DAMPs." (PMID 31924786, 2020). "Necrosis is the main source of damage signals in many tissue and tumor injuries and in anti-tumor immune responses;17–20 therefore, we examined the DAMPs in Arf1-ablated systems." (PMID 31924786, 2020). "Collectively, these data strongly suggest that the anti-tumor effects of Arf1-ablation occur through the induction of a T-cell-dependent immune response." (PMID 31924786, 2020). "Disrupting the Golgi apparatus via inhibition of ADP ribosylation factor 1 (ARF-1) exerts anti-tumor activity against EGFR-activated tumor cells." (PMID 30899432, 2019). "The strong regulation on the protein level is in stark contrast to the transcriptome data, which indeed show a slightly lower ARF1 mRNA level in the WT tumor (1.3-fold higher in the G12V transcriptome data)." (PMID 31805664, 2019). "Most importantly, HDAC inhibitors, such as TSA, can induce the proteasome degradation of EGFR, which in turn inactivating Arf1, leading to suppression of tumor-promoting activity." (PMID 30777099, 2019). "To investigate the role of ARF1 in tumor formation and metastasis, we generated a human TNBC cell line expressing an inducible control (scrambled) or ARF1 shRNA to trigger the knockdown of this ARF isoform." (PMID 26908458, 2016). "We further examined the inhibitory effect of ARF1 knockdown on tumor growth in the mouse xenograft model." (PMID 27213581, 2016). "DU145 cell-derived tumor growth was partially blocked by the knockdown of ARF1, resulting in an approximately 50% reduction in both tumor volume and weight." (PMID 27213581, 2016). "ARF1 plays a central role in intracellular trafficking, Golgi structure maintenance, and mitogenic signaling, and it has recently emerged as a key regulator of tumor progression, with its therapeutic potential being actively explored." (PMID 41465279, 2025). "Additionally, ARF1 disruption sensitizes TNBC (MDA-MB-231) cells to the anti-tumor drugs actinomycin D and vinblastine." (PMID 38533085, 2024). "The question at hand is how the new Arf1 inhibitors in a small number of CSC cells could potentially trigger a robust systemic anti‐tumor response." (PMID 39225354, 2024). "However, further investigation is required to understand the anti‐tumor immunity response regulated by Arf1‐targeted therapy." (PMID 39225354, 2024). "Thus, the Arf1 inhibitors promoted proinflammatory remodeling of the TME to support anti‐tumor immunity." (PMID 39225354, 2024). "Furthermore, T cell activation was blocked after adding apyrase to the medium, indicating that the released ATP from the Arf1‐ablated tumor cells mediated T cell activation." (PMID 39225354, 2024). "Furthermore, GW9662 treatment also prevented the migration of CD3+ T cells toward the Arf1-ablated tumor cells." (PMID 39872623, 2023). "However, we only observed minimal overlap between NLRP3 and the oxidative tumor‐DNA in the Arf1‐ablation‐stimulated DCs." (PMID 37786300, 2023). "We previously reported that Arf1 ablation in CSCs promoted anti-tumor immunity in mice." (PMID 39872623, 2023).
tumor (continued). "Furthermore, we investigated the effect of rabeprazole on lipid droplet accumulation and tumor growth after ARF1 knockdown to prove that the anti-tumor effect of rabeprazole is ARF1 dependent." (PMID 37452028, 2023). "Therefore, the new Arf1 inhibitors represent a new type of anti-tumor immune reagents and can complement and improve current tumor immunotherapy." (PMID 39872623, 2023). "Whereas this effect was mostly dependent on NLRP3, not Aim2, inflammasome, since knockout of Nlrp3, Asc, or caspase‐1 but not Aim2 through CRISPR‐Cas9 technique in DC2.4 cells markedly decreased the protein level of IL‐1β induced by the Arf1‐ablated tumor cells." (PMID 37786300, 2023). "Moreover, we demonstrated that systemic depletion of both type I IFNs and IL‐1β cytokine abrogated tumor regression in mice bearing the Arf1‐ablated tumor cells." (PMID 37786300, 2023). "In summary, our results demonstrated that blocking Arf1 activity could enhance T-cell tumor infiltration through the LPE-PPARγ-NF-κB-CCL5-CCR5 pathway, and the combined treatment of the Arf1 inhibitor and ICBs had synergistic ­anti-tumor effects." (PMID 39872623, 2023). "Moreover, in comparison with the control DCs, both DC2.4 dendritic cells and bone marrow‐derived dendritic cells (BMDCs) significantly increased IFNβ secretion after co‐culture with the Arf1‐ablated tumor cells." (PMID 37786300, 2023). "Furthermore, the combination of the Arf1 inhibitor and programmed cell death protein 1 (PD-1) blockade induced an even stronger anti-tumor immunity." (PMID 39872623, 2023). "Moreover, depletion of the type I IFNs and IL‐1β cytokines abrogate tumor regression in mice bearing the Arf1‐ablated tumor cells." (PMID 37786300, 2023). "To confirm this result, we also pre‐cocultured BMDCs with either the control or Arf1‐ablated tumor cells in the presence of OVA and then re‐cocultured the treated BMDCs with naïve CD8+ OT1 T cells, we observed similar increases of the tumor antigen‐specific CD8+ T cells and IFNγ production." (PMID 37786300, 2023). "However, compared to the isotype treatment, treatments with systemic anti‐IFNAR1 and anti‐IL‐1β antibodies abrogated anti‐tumor effects, as evidenced by significantly increased tumor size and tumor weight of mice bearing the Arf1‐ablated tumor cells." (PMID 37786300, 2023). "Next, we sought to identify the receptors that might mediate signals from tumor cells to DC for activation of the Arf1‐ablation‐stimulated DCs." (PMID 37786300, 2023). "We found that the Arf1‐ablated tumor cell‐challenged dendritic cells could promote expression of T cell stemness marker TCF1 in comparison with that of scramble tumor cell‐challenged dendritic cells." (PMID 37786300, 2023). "Since the Arf1 inhibitor treatment promoted T-cell tumor infiltration and the ICBs modulate T-cell activation, their combination may have a synergistic effect." (PMID 39872623, 2023). "Interestingly, we also found that the Arf1‐ablated tumor cells induced a significant increase in the expression of Cxcl10 in the co‐cultured DCs." (PMID 37786300, 2023). "In this study, we found that the immunogenic factors released from the Arf1‐ablated tumor cells induced and activated a super signaling complex in DCs that further promoted T‐cell infiltration, cross‐priming, and stemness through releasing cytokines and chemokines." (PMID 37786300, 2023). "Since NLRP3 could also be activated by oxidative DNA, we further examined the tumor‐derived oxidative DNA by using a specific antibody in the Arf1‐ablation‐stimulated DCs." (PMID 37786300, 2023). "In addition, the Arf1 inhibitors alone demonstrated superior anti‐tumor immunity in animal tumor models and are good candidates to conduct relevant clinical trials in tumor patients." (PMID 37786300, 2023).
tumor (continued). "To investigate the mechanism that regulates T-cell infiltration into the Arf1-deficient tumors, we first performed bulk RNA sequence with tumor samples from MYC-ON live tumor mouse models with or without Arf1-knockout." (PMID 39872623, 2023). "To investigate this possibility, we first examined oxidized lipids in the Arf1‐ablated CT26 tumor cells and observed a significant increase in the BD‐C11 ratio (green to red) in the Arf1‐ablated tumor cells in comparison with that in the control cells, indicating increased lipid peroxidation." (PMID 37786300, 2023). "We first knocked out Cd36, Tlr2, or Tlr6 in DCs by CRISPR‐Cas9 technique and found that the ASC speck formation was significantly reduced in the Cd36CRISPR‐/−, Tlr2CRISPR‐/− or Tlr6CRISPR‐/− DCs in comparison with that in wild‐type DCs after co‐culture with the Arf1‐ablated tumor cells." (PMID 37786300, 2023). "We found that the Arf1‐ablated tumor cells released HMGB1, oxidized low‐density lipoprotein (oxLDL), and genomic DNA, which might together bind to co‐receptors complex of the CD36/TLR2/TLR6 on the dendritic cell surface." (PMID 37786300, 2023). "In line with this, treatment of mice bearing the Arf1‐ablated tumor cells with anti‐IFNAR1 and anti‐IL‐1β antibodies had markedly reduced frequency of the TNF+IFNg+PD1+CD8+ T cells in tumors in comparison with those in tumors treated with the isotype control antibody." (PMID 37786300, 2023). "We next examined whether the activated DCs contributed to the anti‐tumor immunity induced by the Arf1‐ablated tumor cells." (PMID 37786300, 2023). "Interestingly, a missense mutation of ARF1 (p.L148P), identified in a metastatic GIST tumor, was further verified in a relapsed GIST tumor of the test cohort, suggesting its potential role in GIST progression and therapeutic resistance." (PMID 34805171, 2021). "The wild-type ARF1 or ARF1-T48S mutant was overexpressed in ARF1-deficient HT29 and DLD1 cells, which were subcutaneously injected into flanks of nude mice to establish tumor xenografts, and then azelastine was administered in the tumor-bearing mice." (PMID 33408784, 2021). "Most of the tumor tissues had higher ARF1 expression than adjacent normal tissues." (PMID 33408784, 2021). "Moreover, we stained the tumor tissues with anti-PD-L1 antibody and found that the PD-L1 expressions in the tumor cell surface were reduced after Arf1 knockdown in comparison with those in control." (PMID 31924786, 2020). "We also investigated the effect of Arf1 knockdown on tumor metastasis." (PMID 31924786, 2020). "We further studied the anti-tumor effect of Arf1 inhibition in a mouse liver tumor model." (PMID 31924786, 2020). "Knockdown of ARF1 affected tumor growth by reducing tumor weight and volume." (PMID 26908458, 2016). "To determine whether the phenotype results from ARF1 knockdown is reproducible in the zebrafish-metastasis model, we generated tumor-bearing zebrafish through injecting ARF1 knockdown MDA-MB-231 cells and the knockdown control cells." (PMID 27517156, 2016). "Furthermore, the high expression of ARF1 was not limited to a specific tumor stage." (PMID 41465279, 2025). "Therefore, targeting Arf1 represents a novel anti-tumor immune approach by provoking T-cell tumor infiltration and may provide a new strategy for tumor immunotherapy." (PMID 39872623, 2023). "We demonstrated that ablating the Arf1-mediated lipid metabolism in CSCs resulted in metabolic stress and subsequent cellular responses, including the release of DAMPs, which promoted anti-tumor immunity by activating DCs, thereby enhancing T-cell infiltration and activation." (PMID 31924786, 2020). "The tumor numbers in the Lgr5/Arf1/Apc/IFNγ-KO and Lgr5/Arf1/Apc/Rag1-KO also significantly increased in comparison with those in the Lgr5/Arf1/Apc mice (Lgr5/Apc: 99.6 ± 8.9; Lgr5/Arf1/Apc: 41.0 ± 5.6; Lgr5/Arf1/Apc/Rag1-KO: 90.4 ± 11.0; Lgr5/Arf1/Apc/IFNγ-KO: 73.0 ± 9.5)." (PMID 31924786, 2020).